ATF4 (activating transcription factor 4)
Diseases named in the same sentence as ATF4 in open-access papers (continued):
Sharing a sentence is not in itself a finding about the gene and the disease.
cancer (continued). "Recent studies have indicated that NRF2 and ATF4 regulate cancer cell dependency on either glucose or glutamine through SLC7A11." (PMID 29764521, 2018). "PERK-eIF2α-ATF4 signaling pathway is responsible for cancer growth and resistance against curative treatment." (PMID 30081573, 2018). "The UPR signaling pathway through the PERK-eIF2α-ATF4 signaling pathway also increases tolerance in cancer cells to hypoxic stress." (PMID 30081573, 2018). "ATF4 expression was increased under microenvironmental stresses in tumors, leading to cancer cell adaptation and survival." (PMID 29416636, 2018). "In conclusion, these metabolic disruptions clarify how cancer cells respond to arginine starvation through an ATF4-ASNS axis to switch from an adaptive UPR from ER stress to a non-canonical ER stress response and cell death." (PMID 30393775, 2018). "Various functions of ATF4 promote metabolic homeostasis and cancer cell survival in hypoxic- and nutrient-deprived regions, in particular by affecting amino acid uptake and biosynthesis, autophagy, redox balance and angiogenesis." (PMID 29420561, 2018). "ZFL-mediated ER stress enhanced anti-cancer drug-induced apoptotic cell death, and pretreatment with chemical chaperones or down-regulation of ATF4 and CHOP by small interfering RNA markedly reduced ZFL plus oxaliplatin-induced apoptosis." (PMID 30120227, 2018). "On the contrary, an elevated level of ATF4 expression has been shown in different cancer cell lines." (PMID 30003094, 2018). "Here, we showed that DDX3 positively regulates ATF4 mRNA expression during ER stress induced by Sor treatment of cancer cells." (PMID 29062139, 2017). "Here we identified the RNA-binding protein named DDX3 as a promotor of ATF4 expression in cancer cells treated with sorafenib, an ER stress inducer used as a chemotherapeutic." (PMID 29062139, 2017). "The CHOP–DR5 model sensitizes several chemically challenged cancer cells to extrinsic apoptosis mediated by ROS in vitro, and ATF4 both in vivo and in vitro." (PMID 29230213, 2017). "The anti-cancer effects of the first-in-class molecule ONC201 depend on the activation of an ATF4 signaling pathway." (PMID 29290987, 2017). "In this study, we demonstrate that ATF4 is efficient in counteracting the anti-cancer drug TMZ, leading to chemoresistance." (PMID 28881638, 2017). "PERK/ATF4/CHOP pathway is one of most important pathways to induce cancer cell apoptosis in the UPR." (PMID 26917416, 2016). "For instance, DDIT3 (C/EBP homology protein (CHOP)) and ATF3 are markedly upregulated in response to ATF4 activation, particularly under prolonged stress conditions, which eventually leads to cell death in normal as well as cancer cells." (PMID 26657730, 2016). "In parallel, the protective role of eIF2α phosphorylation and ATF4 synthesis in other types of cancers has been recently described." (PMID 27802179, 2016). "In this report, we investigated the involvement of BTG1 and BTG2 in regulating ATF4, a critical regulator of the integrated stress response both in normal and cancer cells." (PMID 26657730, 2016). "We chose glutamine deprivation for these analyses since glutamine limitation is a physiological stressor known to activate ATF4 and frequently encountered by aberrantly proliferating cancer cells." (PMID 26657730, 2016). "Downregulation of ATF4 was however shown to prevent cancer cells resistance to anticancer drugs, indicating that a minimal expression of ATF4, which is driven by P-eIF2α is nevertheless required for cancer cells survival to chemotherapeutics." (PMID 26556863, 2015). "One called ATF4, which had previously been linked to stress responses, was shown to increase the expression of the gene for ULBP1 in cancer cells." (PMID 26565589, 2015). "Downregulation of ATF4 was shown to prevent resistance of cancer cells to anticancer drugs, indicating that a minimal expression of ATF4 is required for cancer cells survival." (PMID 26556863, 2015).
cancer (continued). "A recent study revealed that the GCN2-PERK-eIF2α-ATF4 pathway is required for survival and proliferation of cancer cells in response to nutrient deprivation." (PMID 25680860, 2015). "The ATF4 and NFκB networks are involved in cellular and molecular functions of cell death, protein synthesis and cancer." (PMID 23637839, 2013). "Vascular endothelial growth factor (VEGF) plays a central role in the angiogenesis of cancer cells, and it is induced by activating transcription factor 4 (ATF4)." (PMID 24330582, 2013). "Our findings highlight a novel signaling pathway through which Celastrol increase Noxa expression, and suggest the potential use of ATF4-mediated regulation of Noxa as a promising strategy to improve the anti-cancer activities of ABT-737." (PMID 23284992, 2012). "Heregulin, a combinatorial ligand for EGFR 3 and 4, has earlier been found to upregulate ATF4 mRNA as well as ATF4 protein in human cancer cells." (PMID 15846300, 2005). "However, chronic ATF4 activation contributes to pathologies including cancer, inflammation, and neurodegeneration." (PMID 42123369, 2026). "Lipid peroxidation–ATF4–Parkin limits the production of lipid peroxidation products by activating mitophagy, and this negative feedback regulatory pathway of lipid peroxidation plays an important role in the process of cancer cell resistance to ferroptosis." (PMID 39679775, 2025). "Furthermore, we demonstrated that Parkin is transcriptionally upregulated by ATF4 to increase mitophagy and subsequently inhibit ferroptosis in cancer cells." (PMID 39679775, 2025). "Future research should aim to unravel how ATF4 activity is dynamically regulated by glutamine flux and how this interplay affects treatment responsiveness across diverse cancer types, ultimately paving the way for more effective, personalized therapeutic strategies." (PMID 40830338, 2025). "The ATF4-Gln axis emerges as a pivotal vulnerability in cancer metabolic processes." (PMID 40830338, 2025). "By supporting the glycolytic shift, ATF4 enhances malignancy, promotes immune evasion, and contributes to therapeutic resistance, making it a central player in the metabolic reprogramming of cancer cells." (PMID 40830338, 2025). "However, the role of mTORC1 and ATF4 in cancer is far from being understood, and further investigations of their role in cancer metastasis in the context of EMT are required." (PMID 41046340, 2025). "Furthermore, the PERK-mediated activation of ATF4 has demonstrated protective functions to inhibit ferroptosis of cancer cells." (PMID 40255561, 2025). "Knockout of ATF4 inhibited ferroptosis inducer‐mediated mitophagy and enhanced erastin‐ or RSL3‐ or cystine deprivation‐induced ferroptosis and lipid peroxidation in cancer cells, and the overexpression of Parkin strongly reversed the effect of ATF4 knockout on cancer cells." (PMID 39679775, 2025). "ATF4 and its downstream effects have emerged as promising therapeutic targets for cancer therapy." (PMID 40598593, 2025). "Our results revealed that, compared with those in wild‐type cancer cells, mitochondrial ROS dramatically accumulated in the early stage of ferroptosis induction and gradually increased with erastin treatment in ATF4‐knockout HCT116 cancer cells or ATF4‐knockout MDA‐MB‐231 cancer cells." (PMID 39679775, 2025). "However, ATF3, ATF5, PMAIP1, DDIT4 and CHOP, which are downstream genes of ATF4, were upregulated by Ocoxin in at least one of the studied cancers, while TRIB3 was overexpressed in all of them." (PMID 40176904, 2025). "The ATF4–lncRNA regulatory network represents a promising therapeutic target in systemic diseases, particularly those involving chronic stress responses such as cancer, fibrosis, and inflammation." (PMID 40777108, 2025). "ATF4 upregulates the expression of adaptive UPR target genes implicated in antioxidant response, amino acid metabolism, and cytoprotective autophagy to maintain cancer cell survival and growth." (PMID 38672243, 2024).
cancer (continued). "Interestingly, in cancer cells, ATF4 and CHOP mRNA expression were significantly induced after DT-061 treatment and only fully rescued to baseline levels after 24 h of drug washout." (PMID 39349971, 2024). "The expression patterns of ATF4 were investigated in 18 human cancers." (PMID 38652216, 2024). "Therefore, the current work provides a thorough analysis of the expression of 27 ATF4 signaling-related genes in 33 different kinds of cancers." (PMID 39139391, 2024). "ATF4 is a stress-induced transcription factor which is frequently upregulated in cancer cells." (PMID 39079386, 2024). "Additionally, PRMT1 binds to ATF4 in a BTG1-dependent manner, methylating ATF4 and promoting the transcription of certain target genes of ATF4, leading to increased apoptosis of cancer cells." (PMID 38326807, 2024). "Interestingly, the ATF4 expression signature has been found to be a predictor of therapy resistance in other cancers." (PMID 37645713, 2024). "Further, ATF4 is considered a cancer target as it has been found to be pro-oncogenic; when upregulated, ATF4 can give cancerous cells the ability to live with limited nutrient delivery, potentially due to its positive relationship with protein degradation mechanisms such as autophagy." (PMID 37749371, 2024). "Recent researches have verified the effects of ATF4 in ferroptosis of cancer cells." (PMID 38652216, 2024). "Characterizing the mechanisms that regulate ATF4-mediated transcription and its effects on cellular metabolism may identify novel targets for cancer therapy." (PMID 39430754, 2024). "Increased CHAC1 levels induce ferroptosis and inhibit GC cell proliferation and survival, indicating that targeting the ATF4/CHAC1 axis could be a promising strategy for ferroptosis-based cancer therapy." (PMID 39534397, 2024). "We postulate that a similarly conserved epitranscriptomic mechanism involving m6A235 demethylating activity by ALKBH5 and/or FTO may contribute to the induction of ATF4 mRNA expression in cancer cells under stress conditions." (PMID 39199320, 2024). "Additionally, eIF3d critically contributed to translational recovery, leading to ATF4 upregulation and enhancing cancer cells’ sensitivity." (PMID 38218922, 2024). "ATF4 has a dual role, influencing ferroptosis sensitivity in a cancer type-dependent manner." (PMID 39104501, 2024). "Our findings are similar to previous studies that reported that ATF4 could influence PSAT1 expression in some cancer cells." (PMID 36732787, 2023). "In addition, the lncRNA BC200 promotes the migration and invasion of cancer cells via the regulation of ATF4 expression, which in turn regulates the expression of PSAT1 in ESCC." (PMID 37147729, 2023). "Several ATF4 downstream targets, such as xCT, a glutamine-cysteine antiporter involved in the xc− system for supporting cellular glutathione synthesis, have been found to serve as mediators of cancer progression." (PMID 37525297, 2023). "This knowledge may help in cancer research to identify cancerous cells that could have circumvented ATF4-mediated apoptosis or cell-cycle arrest." (PMID 36825279, 2023). "Moreover, the cancer cells treated with nelfinavir showed reduced mTOR activity and increased ATF4-mediated SESN2 expression level." (PMID 37284849, 2023). "ATF4 knockout also decreased the progression of cancer in xenograft models of NSCLC." (PMID 35864117, 2022). "TGF-β1 secreted by CAFs upregulates the expression of ATF4 in cancer cells via the SMAD2/3 pathway." (PMID 35646668, 2022).
cancer (continued). "While it is well documented how the ATF4 transcript is translated into protein as a stress response, an important question concerns how the ATF4 message levels are sustained to enable cancer cells to survive the challenges of nutrient deprivation and damaging reactive oxygen species." (PMID 35963851, 2022). "Therefore, we sought to understand what role ATF4 plays in the ability of cancer cells to adapt to the metabolic requirements of increased glutamine metabolism accompanying the “Warburg effect” by using a GAC inhibitor, CB-839, to disrupt glutaminolysis." (PMID 35963851, 2022). "The transcription factor ATF4 drives the expression of ULBP1 gene in cancer cells, while the RNA binding protein RBM4 supports the expression of ULBP1 by inhibiting a new alternative splicing subtype of ULBP1 mRNA, and explains its mechanism of activating the body’s immune system." (PMID 35211154, 2022). "We focused on three genes that are associated with cancer: MAPKAPK2, ATF4, and BCL2." (PMID 36142475, 2022). "Moreover, the secretion of CCL2 in cancer milieu is regulated by activating transcription factor 4 (ATF4), which is produced in response to stress conditions in the cancer environment." (PMID 35408440, 2022). "Additionally, we show that Sirt5 is a transcriptional target of ATF4 necessary for its pro-survival role in response to oxidative stress and conditions that negatively impact glutamine metabolism in cancer cells." (PMID 35963851, 2022). "Additionally, we identify a sirtuin family member, the NAD+-dependent de-succinylase Sirt5, as a key transcriptional target for ATF4 that promotes cancer cell survival during metabolic stress." (PMID 35963851, 2022). "The EIF2α-ATF4/CHOP pathway is regulated by ER stress-related ferroptosis in cancer cells." (PMID 35774124, 2022). "We hypothesized that the different degree of anti-proliferative effect of JPH203 among various cancer cells could be explained by the difference in activation of stress responsive pathway downstream of ATF4." (PMID 35046465, 2022). "ER stress inhibits cancer progression via PERK/ATF4/CHOP signaling." (PMID 37304412, 2022). "ATF4 expression is also found to be upregulated in response to cancer progression, making it an interesting therapeutic target for blocking angiogenesis and adaptation of cancer cells to hypoxia/anoxia." (PMID 35077711, 2022). "ATF4 is a stress-induced transcription factor that is frequently upregulated in cancer cells." (PMID 36476092, 2022). "To verify this hypothesis, we measured ATF4, p-p70S6K levels, and clonogenic ability in cancer cells treated with EAAm mixture alone or EAAm mixture supplemented with Glu, Gly, Asp, or Ala." (PMID 35367410, 2022). "A large number of studies indicated that activated ATF4 could induce cancer cell apoptosis for the oncotherapy." (PMID 33995110, 2021). "The salubrinal increased the protein levels of p-eIF2α and ATF4 in these three cancer cell lines." (PMID 34572286, 2021). "In addition, ATF4 expression was upregulated in cancer cells compared to HBE cells in both the nucleus and cytoplasm." (PMID 33628101, 2021). "In conclusion, the GCN2/ATF4/REDD1 axis induced by amino acid deprivation promotes AKT activation which might be a potential target for cancer therapy." (PMID 34862383, 2021). "However, the specific role of ATF4 in the proliferation, migration, cancer stemness, and gemcitabine resistance of PDAC is still unclear." (PMID 33782384, 2021). "Our data indicate that ATF4 may regulate cancer cell growth and invasion at least partly by regulating Wnt/β-catenin signaling." (PMID 33628101, 2021). "The PERK-eIF2α-ATF4 UPR branch also increases tolerance in cancer cells to hypoxic stress." (PMID 33514437, 2021). "Also, the PERK-eIF2α-ATF4 signaling pathway in cancer cells mediates the up-regulation of VEGF-A transcription." (PMID 33514437, 2021).
cancer (continued). "We found that ATF4 siRNA reduced cancer cell viability and NTPAM-induced cell death was enhanced by ATF4 siRNA, suggesting that ATF4 may be increased by NTPAM for THCA cell adaptation but not cell death." (PMID 33477921, 2021). "The role of ATF4 in malignant tumors has been widely reported, but its role is still controversial, which may be related to specific cell types and molecular context." (PMID 33628101, 2021). "Indeed, many human cancers show activation of the GCN2/ATF4 pathway and depend on it to grow in nutrient-limited environments." (PMID 34862383, 2021). "Firstly, ATF4 may promote cancer progression by regulating the homeostasis of several metabolites, including amino acid and glucose metabolism." (PMID 34976799, 2021). "The crosstalk between CAFs and ATF4 expression in cancer cells was then investigated." (PMID 33782384, 2021). "Since a selective inhibitor of ATF4 has yet to be developed, autophagy inhibition could be a valid approach for cancer treatment." (PMID 34373753, 2021). "Some studies have indicated the promotion of cancer progression by ATF4 12, 13, 15-17." (PMID 33628101, 2021). "ATF4 also has various functions in cancer cells 11, 25, although the issue remains controversial." (PMID 33628101, 2021). "We found that plant hormone GA increased the expressional level of mRNA for the ER stress genes (ATF4, CHOP, sXBP1, and GRP78) in cultured human cells of epidermoid origin—immortalized keratinocytes HaCaT and carcinoma A431cells—but in a slightly different manner for ATF4." (PMID 34834228, 2021). "A deeper understanding of these mechanisms might also facilitate the identification of pharmacological strategies to fine-tune ATF4 activity in different pathologies, such as cancer." (PMID 32228693, 2020). "Autophagy induction by the PERK/eIF2alpha/ATF4 axis in different cancer models." (PMID 32232004, 2020). "We find a strong correlation between DENR•MCTS1 expression and ATF4 activity across cancers." (PMID 32938922, 2020). "Therefore, manipulating ER stress, including suppressing ATF4, has been regarded as an important strategy for therapeutic intervention in cancer." (PMID 33396632, 2020). "Beyond EMT, evaluation of AHR-regulated expression and activity patterns revealed several targets implicated in cancer progression, including members of the matrix metalloprotease family (MMPs, MMP9 and MMP24), asparagine synthetase (ASNS) and the ATF4 transcription factor." (PMID 33214553, 2020). "Speculatively, could the ability of methionine to induce proliferation in cancers rest upon the induction of ATF4, which controls the supply of amino acids and other biosynthetic precursors?" (PMID 33378328, 2020). "Many cancer cells hijack ER stress signaling to promote progression, thus our findings suggest that ATF4-dependent NRF2 activation could be aiding in this process, therefore supporting the interest in targeting NRF2 in cancer treatment." (PMID 32121537, 2020). "This ATF4/NLRP1 axis may also be a common molecular mechanism behind cancer resistance to other therapeutic approaches." (PMID 33396632, 2020). "As such, ATF4 mounts appropriate responses in response to a variety of different stresses, including nutrient deprivation, hypoxia, viral infections, and endoplasmic reticulum stress, and it has been shown to have important roles in cancer." (PMID 32228693, 2020). "In addition, in cancer cells, ER stress-induced activation of ATF4 downstream of eIF2α phosphorylation was reported to promote autophagy by activating DDIT4, which in turn increases eEF2K activity through mTOR inhibition." (PMID 32059483, 2020). "Due to the role of ATF4 in cancer, as well as the role of the other DENR-target genes identified here, this may explain why DENR•MCTS1 have been identified as oncogenes." (PMID 32938922, 2020). "A previous study found that blocking the expression of ATF4 could promote cancer cells to produce much proteins and die." (PMID 33282868, 2020).